YTHDF2 (YTH N6-methyladenosine RNA binding protein F2)
Diseases named in the same sentence as YTHDF2 in open-access papers (continued):
Sharing a sentence is not in itself a finding about the gene and the disease.
pancreatic adenocarcinoma (3 papers, 2020 to 2023). "For instance, METTL3-mediated m6A modification on the 5’UTR of NUCB1 (encoding a calcium-binding protein) mRNA via YTHDF2 (YTH N6-methyladenosine RNA binding protein 2) reader protein in pancreatic adenocarcinoma was associated with poor prognosis." (PMID 36977668, 2023). "Moreover, there was no expression difference of YTHDF2 in kidney renal clear cell carcinoma (KIRC), pancreatic adenocarcinoma (PAAD) and rectum adenocarcinoma (READ)." (PMID 36120577, 2022).
rectal cancer (3 papers, 2021 to 2025). A primary or metastatic malignant neoplasm that affects the rectum. "Several recent studies have confirmed that YTHDF2 can inhibit the expression of SLC7A11 and SLC3A2 through m6A modification, which in turn regulates ferroptosis in rectal cancer cells." (PMID 40948766, 2025). "In the univariate cox analysis, RBM15, YTHDF2, and METTL14 were significantly correlated with prognosis in rectal cancer patients." (PMID 34221955, 2021).
Arthritis (2 papers, 2020 to 2025). Inflammation of a joint. "The up‐regulation of IL‐6R weakened the effect of YTHDF2 on the decrease of arthritis severity score in CIA mice." (PMID 40548546, 2025). "Compared with CIA mice, we observed a significant decrease in arthritis severity scores after YTHDF2 overexpression." (PMID 40548546, 2025). "Furthermore, we demonstrate for the first time that intra‐articular injection of YTHDF2‐overexpressing lentivirus attenuates arthritis severity in CIA models." (PMID 40548546, 2025). "Subsequently, we evaluated the relationship between the clinical symptoms of SLE including LN, NPLE, arthritis, fever, rash, alopecia, ulceration, pleuritis, pericarditis, and the expression of METTL14, ALKBH5, and YTHDF2 in PBMCs." (PMID 32583611, 2020).
astrocytoma (2 papers, 2020 to 2021). "We also found that YTHDF2 expression was higher in astrocytoma than in the other tumor types (oligoastrocytoma and oligodendroglioma)." (PMID 32986017, 2020). "Although YTHDF2 expression was not significantly higher in LGG compared with normal samples, we found that YTHDF2 expression was higher in astrocytoma than in oligoastrocytoma and oligodendroglioma." (PMID 32986017, 2020). "Moreover, high YTHDF2 expression was a prognostic factor in LGG with astrocytoma but not with oligoastrocytoma and oligodendroglioma." (PMID 32986017, 2020). "In addition, higher YTHDF2 expression was associated with poor OS in all LGG and LGG with astrocytoma, but not oligoastrocytoma and oligodendroglioma." (PMID 32986017, 2020).
atherosclerosis (2 papers, 2022 to 2025). A disease characterized by the build-up of fatty material and calcium deposition in the arterial wall resulting in partial or complete occlusion of the arterial lumen. "The increased expressions of METTL3 and YTHDF2 in macrophages of atherosclerosis promoted the occurrence of inflammation." (PMID 40225569, 2025).
autoimmune disease (2 papers, 2022 to 2025). A disorder resulting from loss of function or tissue destruction of an organ or multiple organs, arising from humoral or cellular immune responses of the individual to their own tissue constituents. "Given the role of YTHDF2 in modulating skin and systemic inflammation, we hypothesized that its expression may be altered in autoimmune disorders, where inflammation plays a central role in disease progression." (PMID 41224760, 2025). "Moreover, many reports have explored the relevance between YTHDF2, ALKBH5, and clinical features of autoimmune disease." (PMID 35755020, 2022).
Autoimmunity (2 papers, 2022 to 2023). The occurrence of an immune reaction against the organism's own cells or tissues. "m6A elements (FTO, YTHDF2, YTHDF3, or YTHDC2) might target ISG15, stimulate the expression of ISG15, and activate the type I IFN signaling pathway, playing an active role in initiating the autoimmunity in pSS." (PMID 36465909, 2022).
depression (2 papers, 2022 to 2025). "Another bioinformatic analysis study found that in depression rat models, genes such as Mettl3, Fto, Ythdf2, and Hnrnpc are significantly upregulated, with 66.7% of these genes being core genes regulated by m6A modification, highlighting their crucial role in the onset and progression of depression." (PMID 40590504, 2025). "Next, we performed differential gene analysis of m6A regulators in depression and found that FTO, RBM15B, METTL3, LRPPRC, HNRNPC, ZC3H13, and YTHDF2 were significantly upregulated in depressed rats." (PMID 35480327, 2022).
intervertebral disc degeneration (2 papers, 2024 to 2025). "Our research findings indicate a significant differential expression of YTHDF2 in NP cells of normal and intervertebral disc degeneration (IDD) mice, suggesting its potential as a diagnostic gene for IDD." (PMID 39425013, 2024). "In conclusion, the S263A mutation in YTHDF2 inhibits the proliferation of nucleus pulposus (NP) cells and further exacerbates intervertebral disc degeneration (IDD) in mice." (PMID 39425013, 2024). "Our research has demonstrated that YTHDF2 plays a crucial role in the progression of intervertebral disc degeneration (IDD)." (PMID 39425013, 2024). "In summary, the overexpression of YTHDF2 mitigates the severity of intervertebral disc degeneration (IDD) in mice." (PMID 39425013, 2024). "This study investigates the potential molecular mechanisms by which O-GlcNAc modification of YTHDF2 regulates the cell cycle and participates in intervertebral disc degeneration (IDD)." (PMID 39425013, 2024). "To further evaluate the preventive role of YTHDF2 in vivo in intervertebral disc degeneration (IDD), we established a mouse IDD model using tail suspension (TS) and achieved overexpression or knockdown of YTHDF2 by intravenous injection of lentivirus." (PMID 39425013, 2024).
keloid (2 papers, 2025). An irregularly shaped, elevated mark on the skin caused by deposits of excessive amounts of collagen during wound healing. "In this study, we demonstrated that ALKBH5 inhibits YTHDF2‐m6A‐mediated degradation of RCN1 mRNA to promote keloid formation by activating IRE1α‐XBP1‐mediated ER stress." (PMID 40214031, 2025). "It's reported that YTHDF2 played important roles in many cancers, such as gastric cancer and liver cancer, but few studies extensively explored in keloid." (PMID 40214031, 2025). "Then they constructed a keloid diagnostic Lasso model based on 5 genes and divided keloid samples into high-risk and low-risk groups, showing that m6A regulators ALKBH5, FTO, and HNRNPA2B1 were upregulated in the high-risk group, while YTHDF2 was downregulated." (PMID 40860194, 2025).
lymphoma (2 papers, 2022 to 2025). A malignant (clonal) proliferation of B- lymphocytes or T- lymphocytes which involves the lymph nodes, bone marrow and/or extranodal sites. "Our recent data identified that YTHDF2-m6A-CD19 mediated malignant B cell immune escape from CD19 CAR-T cell therapy, suggesting that YTHDF2 serves as a promising therapeutic target for malignant B cells including B cell leukemia or lymphomas." (PMID 40734692, 2025). "Our findings suggest that YTHDF2 inhibitors may be beneficial in the treatment of lymphomas that specifically originate from the GC reaction." (PMID 35508130, 2022).
male infertility (2 papers, 2022 to 2024). The inability of the male to effect fertilization of an ovum after a specified period of unprotected intercourse. "Conditional deletion of m6A "reader" proteins, Ythdf2, Ythdc1, and Ythdc2, in mouse germ cells has resulted in aberrant regulation of post-transcriptional m6A modification on mRNAs, leading to male infertility." (PMID 38363375, 2024). "To examine the male infertility of Ythdf2‐vKO mice in detail, we first analysed the gross morphology of testes." (PMID 34850470, 2022).
osteoporosis (2 papers, 2025). A condition of reduced bone mass, with decreased cortical thickness and a decrease in the number and size of the trabeculae of cancellous bone (but normal chemical composition), resulting in increased fracture incidence. "Additionally, other research has highlighted FTO, YTHDF2 and CBLL1 as diagnostic biomarkers and m6A‐related molecular patterns in osteoporosis." (PMID 39779466, 2025). "A study involving 80 women with varying BMD analysed differences in the expression levels of the major m6A regulators, leading to the identification of four potential biomarkers for osteoporosis diagnosis: METTL16, CBLL1, YTHDF2 and FTO." (PMID 39779466, 2025). "The YTHDF2 mRNA did not change in the alveolar bone of postmenopausal women with (P11–P20) or without osteoporosis (P1–P10) according to RT‐qPCR analysis." (PMID 40051055, 2025).
ovarian tumor (2 papers, 2021 to 2024). "Moreover, the xenograft mouse model revealed that YTHDF2 depletion markedly hampers ovarian tumor growth in vivo leading to significant reduction of the tumor volume and weight." (PMID 33658012, 2021). "Interestingly, we also found that METTL14 and YTHDF2 expression were decreased in ovarian tumor." (PMID 38505602, 2024).
papillary thyroid cancer (2 papers, 2022 to 2024). "Correlation analysis of immune cells and genes showed the highest negative correlation for YTHDF2/neutrophil in blood samples; consistent with one study that found METTL3 cooperating with YTHDF2 can inhibit papillary thyroid cancer progression via m6A/c-Rel/IL-8-mediated neutrophil infiltration." (PMID 36457545, 2022).
peripheral T-cell lymphoma (2 papers, 2020 to 2022). "Recent studies have discovered repeated exacerbating deletions and mutations of a novel gene, YTHDF2, in peripheral T-cell lymphoma, not otherwise specified (PTCL-NOS), which may imply the functional importance of YTHDF2 in the pathogenesis of this disease." (PMID 35382893, 2022).
pulmonary artery hypertension (2 papers, 2023 to 2025). "YTHDF2 can contribute to pulmonary hypertension through the degradation of Hmox1 mRNA, early macrophage polarization, and vascular inflammation." (PMID 40662138, 2025). "m6A modification and YTHDF2 recognition were found on heme oxygenase 1 (Hmox1) mRNA in alveolar macrophages during the development of pulmonary hypertension." (PMID 40662138, 2025). "Moreover, the METTL3/YTHDF2/PTEN axis was proven to promote hypoxia-induced pulmonary artery hypertension." (PMID 36911406, 2023).
skin cancer (2 papers, 2020 to 2025). "To explore the role of m6A methylation of U6 in YTHDF2’s function in skin cancer, we next assessed the consequence of METTL16 inhibition on the expression of cytokines in the human A431 skin carcinoma cells." (PMID 41224760, 2025). "Indeed, our RNA-seq data analysis showed that genes in the Pathways in cancer are upregulated by YTHDF2 knockdown in HaCaT cells, suggesting a role for YTHDF2 in skin cancer." (PMID 41224760, 2025). "YTHDF2 is reduced in human skin cancer, SLE, and type I diabetes, as compared with normal controls." (PMID 41224760, 2025). "Next, we assessed whether YTHDF2 protein level is altered in human skin cancer." (PMID 41224760, 2025). "Therefore, we assessed expression level of YTHDF1 and its major paralog YTHDF2 across other types of skin cancer to investigate whether this family of genes is essential for all cancer cells or it is a unique feature in MCC." (PMID 31947544, 2020). "Here, the authors show that YTHDF2 recognizes m6A-modified U6 snRNA to prevent aberrant TLR3 activation to inhibit inflammation and skin cancer development." (PMID 41224760, 2025).
Stroke (2 papers, 2020 to 2025). Sudden impairment of blood flow to a part of the brain due to occlusion or rupture of an artery to the brain. "The current study demonstrated that ischemia/reperfusion injury induced the upregulation of YTHDC2, in line with previously observed changes in YTHDF1 and YTHDF2 after stroke." (PMID 41154582, 2025). "Besides, the induction of YTHDC1 was observed after ischemia, which was consistent with the previous report that the abundance of YTHDF1 and YTHDF2 was also altered after stroke." (PMID 33188203, 2020).
type 2 diabetes (2 papers, 2021 to 2022). "Moreover, expression of METTL3, METTL14, and WTAP was reported to be increased in blood from patients with type 2 diabetes (T2D), whilst METTL3 was reported to increase hepatic lipid accumulation through YTHDF2 dependent stabilization of PPARα." (PMID 34950106, 2021).
uterine carcinosarcoma (2 papers, 2020 to 2022). A usually aggressive malignant neoplasm arising from the uterine corpus and less often the cervix. "Firstly, the mutation frequency of YTHDF2 across cancers was analyzed using the cBioPortal database, and the highest mutation frequency of YTHDF2 was detected in Uterine Carcinosarcoma." (PMID 36120577, 2022).
Wilms tumor (2 papers, 2021 to 2025). An embryonal neoplasm characterized by the presence of epithelial, mesenchymal, and blastema components. "Investigations are warranted to verify this assessment and to further evaluate the underlying role of YTHDF2 rs3738067 A>G on the risk for Wilms tumor." (PMID 34539889, 2021). "The current study addresses the association between YTHDF2 gene SNPs and Wilms tumor risk among children of Chinese ancestry." (PMID 34539889, 2021). "Until now, no available reports have been carried out to explore the role of YTHDF2 gene SNPs on Wilms tumor risk." (PMID 34539889, 2021). "We tested whether YTHDF2 gene rs3738067 A>G polymorphism is related to Wilms tumor by genotyping samples of Chinese children (450 cases and 1317 controls)." (PMID 34539889, 2021). "Notably, certain single nucleotide polymorphisms (SNPs) that are present in m1A writers (TRMT6), erasers (FTO), and readers (YTHDC1 and YTHDF2) have been associated with the risk of Wilms tumour risk, emphasising the significant role of m1A modification regulators in Wilms tumour development." (PMID 41017026, 2025). "Thus, here we set as a pioneer to determine the role of YTHDF2 gene SNPs on Wilms tumor risk." (PMID 34539889, 2021). "We hypothesized YTHDF2 gene SNPs may also influence the risk of Wilms tumor." (PMID 34539889, 2021). "The relationship between YTHDF2 and Wilms tumor from the protein level is warranted to be determined." (PMID 34539889, 2021). "The contribution of YTHDF2 gene to oncogenesis has been partly clarified, whereas correlations between YTHDF2 gene SNPs and Wilms tumor risk have not been analyzed." (PMID 34539889, 2021). "The current clinical analysis indicated YTHDF2 rs3738067 A>G could not impact Wilms tumor risk in Chinese children." (PMID 34539889, 2021). "This pilot study provides the first indication that YTHDF2 gene rs3738067 A>G could not impact Wilms tumor risk in Chinese children." (PMID 34539889, 2021). "In all, the results indicated YTHDF2 gene rs3738067 A>G polymorphism could not alter Wilms tumor risk significantly." (PMID 34539889, 2021).
adenoma (1 paper, 2022). A neoplasm arising from the epithelium. "The results indicated that the expression of YTHDF2 was also significantly higher in adenoma and CRC tissues relative to normal tissues, and YTHDF2 knockdown substantially increased the level of CRB3." (PMID 35012593, 2022).
autoimmune hepatitis (1 paper, 2024). Hepatitis caused by autoantibodies. "In autoimmune hepatitis (AIH), upregulation of YTHDF2 decreases the expansion, chemotaxis, and suppressive function of bone-marrow-derived suppressor cells (MDSCs), offering a distinctive therapeutic target for immune-mediated hepatitis." (PMID 39199429, 2024).
bladder tumors (1 paper, 2021). "However, some m6A regulators, including METTL3, RBM15B, YTHDF1, YTHDF2, and IGFBP3, were significantly overexpressed in bladder tumors, and some m6A regulators, including METTL14, METTL16, ZC3H13, and YTHDF3, were markedly downregulated in bladder tumors." (PMID 35004726, 2021).
Bovine mastitis (1 paper, 2025). INFLAMMATION of the UDDER in cows. "In conclusion, this study highlights the essential role of YTHDF2 and IER3 in the inflammatory response of bovine mammary cells to S. aureus infection, providing novel insights into the molecular mechanisms underlying bovine mastitis." (PMID 40521032, 2025).
cervical adenocarcinoma (1 paper, 2024). An adenocarcinoma arising from the cervical epithelium. "Subsequently, the TCGA cervical adenocarcinoma database was organized and genes with relevance to YTHDF2 were extracted for gseKEGG analysis, and the protein processing in the ER pathway was enriched." (PMID 38776708, 2024).
cognitive decline (1 paper, 2025). "For example, altered METTL3 or YTHDF2 activity in excitatory neurons has been shown to impair long-term potentiation and accelerate cognitive decline, while increased FTO-mediated demethylation in microglia promotes pro-inflammatory cytokine production and blood-brain barrier disruption." (PMID 40624693, 2025).
colorectal tumour (1 paper, 2021). "In colorectal tumour tissues classified according to the largest tumour diameter, compared with the < 5 cm group, the expression of YTHDF2 was significantly upregulated in the ≥5 cm group." (PMID 34709763, 2021).
developmental delays (1 paper, 2025). "The loss of Ythdf2 function impedes zygotic genome activation, resulting in developmental delays." (PMID 40894916, 2025).
diabetic kidney disease (1 paper, 2025). Progressive kidney disorder caused by vascular damage to the glomerular capillaries, in patients with diabetes mellitus. "Notably, METTL3 governed PINK1 m6A modification via YTHDF2, driving renal tubular epithelial cell apoptosis and mitophagy in Diabetic Kidney Disease (DKD) pathogenesis." (PMID 41142801, 2025).
dilated cardiomyopathy (1 paper, 2021). Cardiomyopathy which is characterized by dilation and contractile dysfunction of the left and right ventricles. "Through immunoprecipitation accompanied with mass spectrometry analysis, we find that the proteins-interacted with YTHDF2 in cardiomyocytes are mainly related to hypertrophic cardiomyopathy, myopathy and dilated cardiomyopathy, suggesting YTHDF2 may function essential roles on cardiac homeostasis." (PMID 34266473, 2021).
endometrial adenocarcinoma (1 paper, 2021). "The expression of YTHDF1, YTHDF2, and IGF2BP1/2 was increased in women with endometrial adenocarcinoma, whereas a reduction in YTHDC1 was detected." (PMID 34149936, 2021).
Ewing sarcoma (1 paper, 2022). A small round cell tumor that lacks morphologic, immunohistochemical, and electron microscopic evidence of neuroectodermal differentiation. "We therefore have reason to believe that METTL14 and YTHDF2 can serve as prognostic biomarkers for Ewing's sarcoma associated with m6A." (PMID 35487915, 2022). "We were able to find from the pictures of the specific staining by immunohistochemistry that the specific expression of both METTL14 and YTHDF2 in Ewing's sarcoma was higher than their respective expression in the control group." (PMID 35487915, 2022). "Immunohistochemical specific staining revealed higher expression of both METTL14 and YTHDF2 in Ewing’s sarcoma than in the paraneoplastic tissues." (PMID 35487915, 2022).
Fever (1 paper, 2020). Body temperature elevated above the normal range. "This decreased mRNA expression of METTL14 was associated with WBC and M; this decreased mRNA expression of ALKBH5 was associated with CRP, N%, L%, NLR, C3, and fever; and the decreased mRNA expression of YTHDF2 was associated with L%, NLR, C3, and fever." (PMID 32583611, 2020).
fragile X syndrome (1 paper, 2023). A genetic syndrome caused by mutations in the FMR1 gene which is responsible for the expression of the fragile X mental retardation 1 protein. "This suggests that FMRP has a ‘reader’ role and, through its interaction with YTHDF2, contributes to the fragile X syndrome phenotype, a common inherited intellectual disability known to be driven by the loss of functional FMRP." (PMID 36831575, 2023). "In genetic disorders such as fragile X syndrome, the fragile X mental retardation protein (FMRP) has been found to bind to m6A sites and interact with YTHDF2 in the cerebral cortex of mice." (PMID 36831575, 2023).